IL6 (interleukin 6)
Diseases named in the same sentence as IL6 in open-access papers (continued):
Sharing a sentence is not in itself a finding about the gene and the disease.
COVID-19 (continued). "However, until now, the role of HGF in coagulation risk in post-COVID-19 patients is unknown, and how it correlates with D-dimer as a coagulation factor and interleukin 6 as a proinflammatory cytokine that can induce coagulation, especially due to long-term cytokine storms." (PMID 37504277, 2023). "IL-6 was identified as a marker of disease progression and mortality in hospitalised COVID-19 patients." (PMID 37917760, 2023). "Recent studies show that an abnormal diffuse inflammatory cytokine profile can persist in long COVID-19 subjects for at least 8 months, along with the persistent deregulation of IL-1β, IL-6, and TNF-α." (PMID 37887357, 2023). "This study aimed to analyze IL-6 serum level, Acute Respiratory Distress Syndrome (ARDS), and Acute Kidney Injury (AKI) as risk factors for mortality in children with COVID-19." (PMID 37889917, 2023). "IL-6 has been established as a reliable marker for the severity and mortality of COVID-19 in clinical practice, and its antagonist has been shown to reduce mortality in hospitalized COVID-19 patients." (PMID 36992415, 2023). "Studies have been able to identify the correlation between IL-6 levels and COVID-19 diagnosis as well as IL-6 and IL-8 levels with both COVID-19 diagnosis and severity." (PMID 37091818, 2023). "Our results are consistent with the previous evidence, confirming the biological value of this biomarker, similarly to IL-6, which is a strong predictor of severity and mortality in COVID-19." (PMID 36675573, 2023). "In this work, we report for the first time the selective detection of COVID-19 biomarker IL-6 and potential curing drug oseltamivir based on new ratiometric luminescent defect engineered Y-MOF nanoparticles coated with a flexible DNA based stem loop." (PMID 37234896, 2023). "A high level of serum IL-6 is an indicator of cytokine release syndrome (CRS), consistently reported by several studies on COVID-19 and associated with the severity of the disease, such that some authors consider IL-6 an irreplaceable marker of CRS." (PMID 37896877, 2023). "As COVID-19 vaccines elicit inflammatory responses, including the increase in the secretion of IFN and IL-6, which have been implicated in AA pathogenesis, their putative role of triggering AA has been a topic of global interest." (PMID 37176700, 2023). "IL-6 is a proinflammatory cytokine which plays a critical role in chronic inflammation and the cytokine storm characteristic of severe COVID-19." (PMID 37049389, 2023). "This suggests that IL-6 can serve as a marker to indicate the transition from mild to severe COVID-19." (PMID 36672197, 2023). "It inhibits binding of IL-6 to its soluble and membrane receptors and is used in severe presentations of COVID-19 in order to down-modulate inflammation and to avoid respiratory and multi-organ dysfunction." (PMID 37324114, 2023). "These markers were associated with circulating indexes of respiratory disease severity (Horowitz index and alveolar-to-arterial oxygen gradient), inflammation (interleukin-6 and interleukin-10), and hypercoagulability (D-dimer) in COVID-19 patients with ARDS." (PMID 37408073, 2023). "Upon admission, male patients with acute COVID-19 exhibited high levels of circulating IL-6 (139.28 ± 48.95 ng/mL), which significantly decreased following the administration of 1α,25(OH)2D3 (2.65 ± 0.92 ng/mL)." (PMID 37375800, 2023). "This also shows that IL-6 can be used in monitoring patients with COVID-19 since IL-6 values can prognosticate disease progression and mortality even beyond 14 days after the onset of infection." (PMID 36926338, 2023). "It’s interesting to note that B cells from people with acute COVID-19 showed an imbalance between the cytokines IL-6 and IL-10 in response to the activation of Toll-like receptors, leaning toward a pro-inflammatory profile." (PMID 37767093, 2023).
COVID-19 (continued). "One early study found a significantly decreased D-dimer, ferritin, CRP, IL-6 and procalcitonin in COVID-19 patients who underwent PLEX." (PMID 37712090, 2023). "The IL-6 cytokine has been identified as the most abundant inflammatory cytokine accumulating in COVID-19 patients and the most harmful in the progression of the disease." (PMID 37891903, 2023). "HD + COVID-19 patients showed higher inflammation, measured as higher levels of C-reactive protein and IL-6, and lower lymphocytes and higher aspartate aminotransferase in routine clinical tests on the sampling day compared to uninfected HD patients." (PMID 36675231, 2023). "Several studies have already highlighted the direct correlation between IL6 levels and COVID-19 severity." (PMID 37108262, 2023). "As one of the most important pro-inflammatory factors, IL-6 was significantly increased in the serum of COVID-19 patients compared with healthy people." (PMID 37601070, 2023). "Further studies are needed to elucidate how adipokines, especially adiponectin, affect the progression and prognosis of COVID-19, also in the context of immunomodulatory treatment with corticosteroids and IL-6 inhibitors." (PMID 36960389, 2023). "The majority of studies have reported that proinflammatory cytokines, such as interleukin (IL)-6, tumor necrosis factor α (TNFα), and IL-1β, are related to COVID-19 pathogenesis." (PMID 37515185, 2023). "Herein, we confirm that result, i.e., out of 27 COVID-19 patients that had IL-6 results of >25 pg/mL at admission, later, 19 (70.4%) of these required mechanical ventilation." (PMID 36983566, 2023). "IL-6 is known to elicit the most dangerous effects of the COVID-19 cytokine storm, as well as to dampen the recruitment and development of lymphocytes; therefore its blockade was suggested as a possible therapy, especially for patients with a severe infection." (PMID 36768649, 2023). "Recent evidence suggests that in COVID-19, MCs play a crucial role in inducing inflammation by releasing pro-inflammatory cytokines, such as IL-6 and IL-1beta." (PMID 37511729, 2023). "Many reports describe COVID-19 as a purely pro-inflammatory disease, requiring therapy strategies dampening a cytokine storm by e.g., glucocorticoids or anti-IL-6." (PMID 36851312, 2023). "It is an established driver of acute responses to COVID-19, and treatment with anti-IL-6 monoclonal antibodies reduces mortality in severe COVID-19." (PMID 36995412, 2023). "The targeting of the IL-6 signaling pathway is a promising strategy for managing chronic inflammation and trained immunity post-COVID-19." (PMID 38090572, 2023). "In this study, we described two groups of immunologically distinct COVID-19 patients, based on their IL-6 response." (PMID 37081872, 2023). "Recent studies revealed that elevated levels of TNF-α and IL-6 were observed in COVID-19 patients with injury." (PMID 36671484, 2023). "Though canonical markers of inflammation (IL-6, TNF-α, and CRP) have previously been shown to be associated with higher mortality in supercentenarians and COVID-19 patients, there is an intricate interplay between immune cells and cytokine secretion." (PMID 37928548, 2023). "A previous study showed that high IL-6 serum levels are correlated with HERV-W ENV antigenemia in COVID-19 and, in vitro, that IL-6 can be induced by SARS-CoV-2 in healthy donor’s PBMC but it appeared much later that HERV activation in “responding” donors." (PMID 37524719, 2023). "When the COVID-19 group was subdivided, only long-COVID-19 showed significantly higher IL-1β and IL-6 SARS-CoV-2 S protein-specific values compared to healthy individuals." (PMID 37018291, 2023). "Increased cytokines and other pro-inflammatory factors, such as TNF, IL-1, IL-6, and IL-8, are believed to contribute to endothelial injury and subsequent pro-thrombotic events in COVID-19." (PMID 38138084, 2023).
COVID-19 (continued). "IL-6, an important player in COVID-19, binds IL-6R and gp130 receptors to activate JAK/STAT-3 pathway and then contributes to the CRS observed in COVID-19 and possibly in Long COVID patients." (PMID 36947108, 2023). "In this experiment, we have demonstrated that Sulodexide inhibits IL-6 secretion from endothelial cells at a later stage of COVID-19." (PMID 38188630, 2023). "The expression of IL-6, another important player in the so-called cytokine storm occurring in the most severe COVID-19 patients, was also significantly increased in infected HBMEC, and it is known to be modulated by its promoter methylation." (PMID 36992454, 2023). "As for cytokine, it was revealed that IL-2, IL-4, IL-6, and IL-10 were abnormally activated in COVID-19 patients and that IL-6 levels correlated with disease severity." (PMID 37533853, 2023). "IL-6 has been reported as a key contributor to disease complications and is a strong predictor of survival in COVID-19 patients." (PMID 37075454, 2023). "Relative abundance of most cytokines was elevated in the plasma of individuals with moderate, severe, and fatal COVID-19, with IL-6 reaching the highest levels among them." (PMID 36852984, 2023). "Despite the lack of disease severity data, our findings are consistent with previous research and suggest that IL-6 can be used as a marker for COVID-19 disease severity." (PMID 36608055, 2023). "In the present pilot study, we evaluated the potential of modulation of the IL-6 (colchicine), IL-17 (ixekizumab), and IL-2 signaling pathways to treat moderate to critical COVID-19 in hospitalized patients." (PMID 37075454, 2023). "In COVID-19, the cytokine IL-6 showed high levels of interest due to secreting the protein in the lung epithelial cell." (PMID 38013836, 2023). "IL-6 is an anti- and pro-inflammatory cytokine whose expression is highly elevated in COVID-19 patients with lung infection." (PMID 37759873, 2023). "In non-COVID-19 patients, only IL-6 was able to distinguish infiltrate above the median from infiltrate below the median (AUC = 0.81, p < 0.05, cut-off 15.3 pg/ml: sensitivity 77.8%, specificity 63.2%), opposite to DPP3 (AUC = 0.56, p = n.s)." (PMID 37733154, 2023). "Cytokines, notably interleukin-6 (IL-6), increase considerably in patients with severe corona virus disease 2019 (COVID-19)." (PMID 37960722, 2023). "IL-1β induces the production of IL-6, another abundantly detected cytokine in severe COVID-19 patients." (PMID 36661317, 2023). "A study that analyzed cytokine levels in patients with COVID-19 found that the serum levels of IL-6, IL-8, and IL-10 were significantly higher in patients with a more severe form of the disease." (PMID 37969879, 2023). "Most notably, however, data from this study also indicate a significant increase in blood plasma levels of the inflammatory cytokine IL-6 between 3 months and 18 months after COVID-19 recovery." (PMID 36835948, 2023). "Here, we confirm this result, i.e., of the 27 patients with COVID-19 who had IL-6 results >25 pg/mL on admission, 19 (70.4%) of them later required mechanical ventilation." (PMID 38203482, 2023). "Tocilizumab models show that, through IL-6 signalling blockage, the drug can alter the activity of several proteins involved in COVID-19-evoked ARDS." (PMID 36791125, 2023). "Individuals with obesity also have higher levels of circulating pro-inflammatory cytokines (such as TNF-α, IL-6 and C-reactive protein), further aggravating the cytokine storm observed in COVID-19 patients." (PMID 37112923, 2023). "Cytokine concentration (TNF-alfa, IFN-gamma, IL-2, IL-4, IL-6, and IL-10) increased greatly after in vitro exposure to the COVID-19 vaccine." (PMID 37686102, 2023). "The administration of a probiotic mix to 19 patients discharged after hospitalization for COVID-19 indicated that serum citrulline levels, IL-6, IL-12RA, and TNF-α were significantly reduced at the end of treatment (week 8) compared to baseline levels." (PMID 37763251, 2023).
COVID-19 (continued). "IL-6 is a pleiotropic cytokine with both anti- and proinflammatory activities and was shown to be significantly increased in severe COVID-19 cases compared to mild cases." (PMID 36672197, 2023). "In addition, serum levels of both IL-6 and IL-10 correlated positively with pulmonary lesion volumes on chest CT scans caused by COVID-19, while others argued that the TNF-α/IL-10 ratio could readily estimate progression to acute respiratory failure during COVID-19." (PMID 37568402, 2023). "The adhesion molecules P-selectin and VCAM-1 were more upregulated in male patients, while the IL-6 levels were generally increased in our COVID-19 and/or post-COVID-19 patients." (PMID 37896963, 2023). "We also analyzed the IL-6 levels through the COVID-19 progression phases according to severity: per the CCDC score, there was a sevenfold and threefold decrease in the MI (p = 0.006) and SI groups, respectively, for days 1–9 versus days 10–16." (PMID 37147677, 2023). "Another study showed that IL-6 and C-reactive protein levels on the first day of admission were predictors of mortality in severe COVID-19." (PMID 37969879, 2023). "As a result, blocking the activity of IL-1 and IL-6 has been proposed as a potential therapeutic strategy for the treatment of COVID-19." (PMID 37046952, 2023). "IL-6 showed increased expression along with disease severity, and it appears as a potential predictor for the progression of COVID-19 to severe disease." (PMID 37529051, 2023). "IL-6 inhibitor has been shown to be effective in patients with severe COVID-19 and have become one of the standard treatments against COVID-19, but the best beneficiary group needs to be evaluated." (PMID 37391394, 2023). "Different studies reported that among inflammatory cytokines, IL-6 is an early indicator in the acute phase in COVID-19 patients, indicating liver injury." (PMID 36671484, 2023). "The scarce longitudinal data on cytokines in COVID-19 patients include decrease levels of IL-6 in survivors, of other proinflammatory cytokines by day 16, and of IL-6 two days after convalescent plasma transfusion." (PMID 37147677, 2023). "IL-6 and PCT have been associated with COVID-19-related in-hospital death, and were predictors of all-cause mortality in dialysis patients." (PMID 37501590, 2023). "Nasal administration of a fully human anti-CD3 monoclonal antibody (Foralumab) reduced lung inflammation as well as serum IL-6 and C-reactive protein in moderate cases of COVID-19." (PMID 36881624, 2023). "In conclusion, the combination of BCc1 and Hep-S inhibits IL-6 as a highly important and well-known cytokine in COVID-19 pathophysiology and presents a promising view for immunomodulation that can manage CSS." (PMID 37951972, 2023). "At the turn of the pandemic declaration of the World Health Organization, a couple of paper reported clinical results of studies carried out on COVID-19 patients in Wuhan, China, in which the plasma levels of IL-6 and IL-1024, and of IL-625 were measured." (PMID 36941368, 2023). "Tocilizumab, an anti-IL-6 antibody, can help decrease inflammation and mortality in COVID-19 subjects." (PMID 36673615, 2023). "In the chi-square test, a significant relationship was found between IL-6 levels and COVID-19 severity (P = 0.004; P <0.05)." (PMID 38099004, 2023). "Patients who had severe COVID-19, were shown to have higher levels of resistin, IL-6, TNFα and reduced adiponectin/leptin ratios suggesting that adipokines are likely to play an important role in disease pathogenesis." (PMID 37676889, 2023). "For example, myeloid cells are the main source of pro-inflammatory cytokines, such as IL-6, as observed in COVID-19 patients." (PMID 37528224, 2023). "IL-6 is one of the key factors and its level is positively correlated with the severity of COVID-19." (PMID 37686271, 2023). "Our study confirmed what was expected: all COVID-19 patients had increased IL-6, with MAFLD patients expressing significantly higher levels." (PMID 37629728, 2023).
COVID-19 (continued). "Laboratory parameters like elevated CRP and IL-6 predicted COVID-19 disease severity and the need for mechanical ventilation in COVID-19 patients." (PMID 38152668, 2023). "Additional evaluation showed that the mean IL-6 levels in acute COVID-19 patients were higher than those in healthy individuals (mean difference = 22.01 pg/ml, 95% CI = 11.5–32.51 pg/ml, I2 = 96%, P < 0.0001)." (PMID 37095536, 2023). "Along with TNF-alpha and IFN-gamma, high levels of IL-6 became one of the most important prognostic markers in COVID-19." (PMID 37243282, 2023). "More interestingly, the current investigation showed that the IL-6 level can be used to assess the production of NAbs after COVID-19 vaccination." (PMID 38813035, 2023). "Databases were systematically searched for articles with data on long COVID-19 and IL-6 levels published before September 2022." (PMID 37095536, 2023). "IL-6 levels were significantly higher (Mann–Whitney test, p = 0.0132) in the vaccinated COVID-19 patients (75.1 ± 37 vs. 56.8 ± 50.9 pg/mL) at diagnosis." (PMID 37896963, 2023). "Excessive, deleterious cytokine storms driven primarily by significant increases of IL-6/sIL-6R, IL-8, and IL-10 levels were also observed in severe COVID-19 patients compared with mild COVID-19 patients." (PMID 36851954, 2023). "Our study analyzes IL-6 and its soluble receptor complex (sIL-6R and sgp130) in critically ill COVID-19 patients who suffered severe respiratory failure from the perspective of the second COVID wave of 2020." (PMID 37887780, 2023). "Consistent with previous reports, COVID-19 patients displayed higher levels of TNFα, IL-1β, IL-6, IFNα, IFNβ, TGFβ and IL-10 in comparison with HD." (PMID 37063865, 2023). "Probiotics also have an immunomodulating role in the cytokine storm (IL-1B, IL-6, IL-15, IL-15, IL-17 IFN-g, TNF-a), and it can thus be deduced that probiotics are involved in fighting the cytokine storm associated with COVID-19." (PMID 37049576, 2023). "IL-6 has been demonstrated to be a key biomarker of COVID-19 severity, and various demographic and clinical characteristics have been linked to its levels and the severity of COVID-19 infection." (PMID 37960722, 2023). "The available data from 17 cohorts of 16 studies were used to estimate differences in IL-6 levels between long COVID-19 patients and healthy individuals." (PMID 37095536, 2023). "Clinical laboratories had to rapidly adapt to these changes, reorganize their resources, create specific profiles for COVID-19 patients and incorporate new tests (i.e., IL-6)." (PMID 37363429, 2023). "The data of patient #4 revealed the potential for PPHM COVID-19 data to be more informative than IL-6 or CRP data." (PMID 37894092, 2023). "The detection range for the proposed aptamer-functionalized SiNW-FET is enough to measure the IL-6 levels expressed in COVID-19-infected patients and to distinguish the mild and severe degrees of pathological conditions." (PMID 36679421, 2023). "Multiple immunomodulatory monoclonal antibodies, directed against cytokines such as against tumour necrosis factor alpha (TNF-α), Interleukin (IL)-1, and IL-6, were assessed in COVID-19 patients." (PMID 38203525, 2023). "Among the cytokines evaluated, IL-6 was the most related to a worse prognosis in patients with COVID-19, as it was increased in most patients, especially in those with more severe disease." (PMID 37903875, 2023). "To further evaluate the impact of IL-6 on tyrosine nitration and pattern expression of purinergic ectoenzymes, we performed in-vitro experiments in which cultured PBMCs from COVID-19 patients were stimulated with two IL-6 concentrations." (PMID 37818368, 2023). "These cytokines include IL-6, a primary mediator of cytokine storm, which is a life-threatening condition seen in some patients with COVID-19, characterized by extreme increases in pro-inflammatory cytokines and an uncontrolled immune response." (PMID 36851722, 2023).